CCR3 (C-C motif chemokine receptor 3)
Diseases named in the same sentence as CCR3 in open-access papers (continued):
Sharing a sentence is not in itself a finding about the gene and the disease.
tumor (continued). "This process is dependent on the secretion of the chemokine CCL7 by adipocytes, which diffuses from PPAT to the peripheral zone of the prostate, stimulating the migration of CCR3 expressing tumour cells." (PMID 26756352, 2016). "Further experiments indicated that CCL28 also plays key roles in tumor angiogenesis by targeting chemokine receptor CCR3 on vascular endothelial cells." (PMID 27250766, 2016). "Very interestingly, the proportion of tumours expressing moderate and high levels of CCR3 increased in 4+3 compared with 3+4 Gleason scored tumours." (PMID 26756352, 2016). "In Hodgkin lymphoma and cutaneous T cell lymphoma, CAFs secrete the chemokines CCL11 and CCL26 that recruit CCR3(+) T lymphocytes into the tumor and produce high levels of IL-4, a signature of a Th2-dominant microenvironment." (PMID 25110692, 2014). "In anaplastic large cell lymphomas, the CCR3/CCL11 interaction promotes tumor cell proliferation and inhibits apoptosis through ERK1/2, Bcl-xL and the production of survivin." (PMID 25110692, 2014). "In addition, two key chemokines, CXCL9 and CCR3, which are known to promote CD8+ T cell recruitment into the tumor microenvironment (TME), were upregulated in the high-risk group." (PMID 41584042, 2026). "Furthermore, recombinant human CCL11 has been shown to expand the CD4+CD25+Foxp3+ regulatory T-cell (Treg) population while upregulating both CCR3 and Foxp3 expression in tumor microenvironments." (PMID 40429807, 2025). "Upregulation of CCR3 could also indicate an enhanced inflammatory response, where the tumor secretes chemokines that recruit immune cells expressing CCR3." (PMID 40484866, 2025). "In the tumor microenvironment, IL-5 activated CC motif chemokine receptor type 3 (CCR3)." (PMID 37005677, 2023). "Given the role of CCR4 and CCR3 in recruiting T cells and other immune cells to the tumor, the enhanced expression of these chemokine receptors on transferred Foxp3UP CD8 T cells may also explain their increased numbers in the tumors." (PMID 36045586, 2023). "CCR1, CCR2 and CCR3 were reported to be potential receptors of CCL7 in tumor microenvironment." (PMID 35715847, 2022). "Additionally, we verified that CCL11 expression from surrounding CAFs directly affects the tumor behavior and promotes its aggressiveness by targeting CCR3." (PMID 35804913, 2022). "On the other hand, we found that the chymotryptic serine proteinase Cma1, the endogenous opioid polypeptide hormone Penk, Guanine nucleotide-binding protein Gnai1 and the chemokine receptor Ccr3 were among the most down-regulated genes in SSMs after the influence of a local tumor mass." (PMID 34168645, 2021). "Interestingly, tumor cells migration measured in Boyden chambers was decreased when culture medium was supplemented with the CCR3 antagonist SB-297006 (*p < 0.05)." (PMID 33608009, 2021). "To investigate this hypothesis, we explore whether the human bone metastatic sites were enriched with tumor cells expressing CCR3 using two different strategies." (PMID 33671469, 2021). "To investigate the functional role of eosinophils in mediating tumor regression, we intraperitoneally injected an isotype control or anti-mouse CD193 (CCR3) antibody (clone# 6S2-19-4) 13 or anti-mouse CD170 (Siglec-F) antibody (clone #238047) 14 to deplete eosinophils in vivo." (PMID 33754022, 2021). "In addition to the recruitment of eosinophils, CCL26 has also been shown to cause TAM recruitment depending on CCR3 and CX3CR1-dependent recruitment of MDSC into the tumor niche." (PMID 33182504, 2020). "Our results suggest that metastatic tumor cells induce CCL7 expression in LECs that, in turn, might attract further CCR3-positive tumor cells promoting tumor cell dissemination through lymphatics." (PMID 31963450, 2020). "Previous studies have proven that CCL28 could recruit CCR3+ regulatory T cells (Tregs) homing to the tumor, which thereafter could promote tumor immunosuppression and tumor angiogenesis by secreting VEGF13." (PMID 27250766, 2016).
tumor (continued). "As speculated, CCL7 and CCR3 mRNA expression levels in liver metastatic tissue were significantly higher than those in primary tumor tissue." (PMID 27167205, 2016). "Persistent in vivo CCR3 depletion was confirmed by immunohistochemistry on excised tumours." (PMID 26756352, 2016). "Furthermore, depletion of CCR3 totally abrogated the differences in tumour size observed between lean and obese mice after injection of the parental cell line." (PMID 26756352, 2016). "Similar to the results from tumor samples, CCR3 was highly expressed on both of the two cell lines." (PMID 27250766, 2016). "Alternatively, this could mediate protection against tumour progress by recruitment of eosinophils and/or other CCR3+ leukocytes with an antitumourigenic role." (PMID 17672898, 2007). "In addition, it is also able to bind to CCR3, thus promoting tumor angiogenesis." (PMID 36072582, 2022). "However, some tumors, including colorectal cancer, have been reported to show an increased expression of eotaxins, which indicates the potential benefits of immunotherapy in which anti-tumor cells will have an increased expression of CCR3, a receptor for eotaxins." (PMID 33182504, 2020). "Finally, we observed in a small series of eight patients that CCR3 expression was slightly upregulated in tumour cells present at the invasive front compared with cells from the centre of tumours, this effect being more pronounced in overweight and obese patients." (PMID 26756352, 2016). "Confocal imaging highlighted the presence of CCR3-CLC-P/Gal10 double-positive cells characterised by a bilobed nucleus, revealing that eosinophils indeed infiltrated the tumour." (PMID 39471751, 2024). "CCR1, CCR2B, CCR3, and CCR5 are receptors for CCL8 that are expressed in both immune and tumor cells and play pro-cancer and anti-cancer roles." (PMID 38136340, 2023). "ThyroidPrint® is a novel q-PCR-based ten-gene classifier with its signature representing both the tumor microenvironment (CXCR3, CXCL10, CCR3, CCR7, and CXADR) and tumor epithelial cells (TIMP1, CLDN1, KTR19, AFAPL2, and HMOX1)." (PMID 37671897, 2023). "For the further investigation of the expression of the three genes (CCR3, CCL14, CCL20) in HCC tissues, RT-qPCR was applied to the detection of mRNA expression of the three genes between HCC tissues and adjacent non-tumor tissues." (PMID 37545521, 2023). "The chemokine CCL7 secreted by PPAT was reported to mediate interactions between PPAT and PCa cells through the CCR3/CCL7 axis, promoting the extraprostatic extension of tumour." (PMID 37042512, 2023). "The RT-qPCR results demonstrated remarkable discrepancies in the expression of CCL14, CCL20, and CCR3 between HCC and its paired adjacent non-tumor tissues." (PMID 37545521, 2023). "In contrast to Th1 cells, Th2 cells express CCR3, CCR4, and CCR8 receptors on their surface and can promote tumor progression by exerting immunomodulatory functions in response to stimulation by the corresponding ligands." (PMID 37063892, 2023). "However, studies in other types of cancer have shown that CCR3 plays a major role in promoting tumor progression and is strongly associated with poor prognosis of patients, with its role in the TIME exhibited through the recruitment of TAMs to facilitate tumor progression." (PMID 37545521, 2023). "A variety of chemokine/chemokine receptor strategies have been utilised in immunotherapeutic T cell preclinical work to facilitate CAR T cell targeting to tumour masses, including the exploiting the CXCR3, CXCR2, CCR5, CCR2, and CCR3 axes." (PMID 35205725, 2022). "Chemokine CCL5 participates in the proliferation and migration of tumor cells, as well as angiogenesis and lymphangiogenesis, by binding to receptors CCR5, CCR3 and CCR1." (PMID 36514094, 2022). "The differential analysis also confirmed the high expression of CD74, HLA-DRA, C7, CCL12, and CCR3 in CAFs from P-LN but lower expression of VIM, APOD, MMP11, TAGLN, and CDKN2A compared with that in the primary tumor." (PMID 36569924, 2022).
tumor (continued). "Although CCR1, CCR2, CCR3, and CCR5 are widely recognized as the main functional receptors of CCL7, PCa is mainly dependent on the CCR3/CCL7 signaling axis, which contributes to the tumor microenvironment." (PMID 35406450, 2022). "It is also worth investigating which ligands CCL8 binds to, including CCR1, CCR2, CCR3, and CCR5, and thus how it affects the downstream signaling pathways that lead to changes in the biological behavior of tumor cells." (PMID 36072582, 2022). "CCL5 is recognised by a range of chemokine receptors that are maintained on ex vivo stimulated T cells such as CCR1, CCR3, and CCR5, making CCL5 a good candidate for tumour-specific expression to target adoptively transferred lymphocyte migration." (PMID 35205725, 2022). "CCR3 staining was then performed in this second TMA and scored by two pathologists into low-, intermediate- and high-expressing tumours." (PMID 26756352, 2016). "In summary, the chemokine, CCL11, along with its cognate receptor, CCR3, have been identified as major factors influencing GBM tumor development." (PMID 27119233, 2016). "Previous studies have shown that myeloid-derived suppressor cells (MDSCs), tumor-infiltrating lymphocytes (TIL), MSCs, CAFs and CSLCs can produce CCL5 and that cancer cells express the CCL5 receptors CCR1, CCR3, and CCR5." (PMID 25788271, 2015). "Expression of the inflammatory chemokine receptors, CCR1, CCR2, CCR3, CCR5 and CX3CR1, was significantly enriched on both Foxp3+ and Foxp3− CD4+ T cells within the tumours when compared with spleens and lymph nodes." (PMID 25495686, 2015). "Since CCR3 is strongly expressed on migrating T lymphocytes, we suspected that RANTES was the major chemoattractant of T lymphocytes to the tumor microenvironment." (PMID 21647415, 2011). "Clinically, CCR3 expression in tumor specimens shows a positive correlation with advanced histological grades, suggesting that CCL11/CCR3 signaling may drive tumor progression and metastatic potential in CCR3-positive RCC." (PMID 40429807, 2025). "Key chemokines involved in CD8+ T cell recruitment (CCR3, CXCL10, CXCL9) and their receptors (CCR2, CCR5, CXCR3) were consistently downregulated in FAM174B-high tumors, potentially limiting effector immune cell trafficking to the tumor microenvironment." (PMID 40959568, 2025). "Using an eosinophil gene signature (SIGLEC8, RNASE2, RNASE3, IL5RA, and CCR3), it was found that eosinophil infiltration inside the tumor correlates with increased CD8+ T cell and IFN-γ signatures and was shown that tumor eosinophils enhance CD8+ T cell activation, leading to tumor eradication." (PMID 39496729, 2024). "We evaluated the immunogenicity and anti-tumor effect of CCL11-E6E7 in mice with or without CCR3 + cells by using an anti-CCR3 monoclonal antibody to deplete CCR3 positive cells." (PMID 38459592, 2024). "Tumour biopsies from subjects displaying low and high absolute eosinophil counts (AEC) in the peripheral blood (85 and 1019 eosinophils/μL of blood, respectively) were stained with DAPI and fluorescently labelled for CCR3 and CLC-P/Gal10." (PMID 39471751, 2024). "As CCR3 is the major receptor of CCL11, we sought to determine whether CCR3 + cells were essential for immunogenic improvement and tumor eradication in vivo." (PMID 38459592, 2024). "Both CCR3 and IL17B have been found to be related to the role of tumor microenvironment in regulating tumor growth and metastasis, and may be new immunotherapy targets." (PMID 37316840, 2023). "MDSCs have several chemokine receptors, including CCR1, CCR2, CCR3, CCR5, CCR12, CXCR2, CXCR4, and C5aR1.25In the current study, MDSCs may express CCR1, the receptor of CCL9, which mediated the migration of MDSCs to tumor tissue." (PMID 38046278, 2023). "Ten chemokine receptors (CXCR1, CXCR2, CXCR4, CXCR6, CCR3, CCR6, ACKR4/CCRL1, CCLR2, CX3CR1, and ACKR1/DARC) were identified as differentially expressed from the DEG analysis between Black, White and Asian patient normal and tumor samples." (PMID 35754051, 2022).
tumor (continued). "Interestingly, TGF-β, which is secreted by tumor cells and tumor-infiltrating regulatory T cells, enhances the expression of chemokine receptors CCR1, CCR3, CCR5, CCR6, and CXCR4 on DCs, thereby driving DC migration to the TME." (PMID 34290401, 2021). "Then, we used flow cytometry to label and analyze the number of CCR3+, CCR9+, CCR10+, CXCR2+, CXCR5+, and CXCR6+ cells expressed different isotype antibodies including IgA, IgG, and IgM in the lung metastases of cKO and control tumor-bearing mice." (PMID 33707428, 2021). "CCL15 also acts on non-cancer cells in the tumor, for example causing angiogenesis mediated by CCR1 and CCR3 on vascular endothelial cells." (PMID 33182504, 2020). "As CCR3 is also expressed on eosinophils and subpopulations of Th2 cells, CCR3+ cells secreting CCL11 and IL-4 may produce a Th2-dominant microenvironment, which is suitable for tumor growth." (PMID 29915722, 2018). "Importantly, cancer cells in human primary tumor tissues that were CCR1, CCR3 or CCR5-positive expressed high levels of vimentin." (PMID 25788271, 2015). "To understand the cause of CCL5-mediated reduced survival in PDAC, we hypothesized that immune cells responsive to a CCL5 chemotactic gradient (through expression of the cognate receptors CCR5, CCR3, or CCR1) could be potential contributors to an adverse tumor immune environment." (PMID 39656086, 2024). "However, although expression of Ccl5 and its receptors Ccr1 and Ccr3 were not affected by IL-6Rα deficiency in CAC, expression levels of Ccl20 and of its unique receptor Ccr6 were reduced in knockout tumours." (PMID 29695802, 2018). "The CCR3+ tumor cells abundantly express IL-4 but not IFN-γ." (PMID 29915722, 2018). "Intriguingly, adipocyte-mediated chemokine secretion as part of a chemokine axis involving chemokine ligand 7 (CCL7) and its receptor chemokine receptor 3 (CCR3) may mediate interactions between local peri-prostatic fat (PPF) and PC to promote tumour progression." (PMID 28753854, 2018). "As opposed to MF/SS, the tumor cells of PCALCL express CCR3." (PMID 29915722, 2018). "In addition, expression of CCR3, the receptor for CCL11, was also increased in the tumor." (PMID 27119233, 2016). "CCR3-deficient tumours were smaller in size, and the surrounding PPAT was still present and thicker than in control tumours, demonstrating that, in these conditions, adipose tissue is not modified by the tumour." (PMID 26756352, 2016). "Since peritumorally expressed CCR3 might be a confounding factor for tumor initiation and subtype development, we therefore confined our analysis in samples without peritumoral stromal expression of CCR3." (PMID 27086913, 2016). "Moreover, CCR3 and CCR10 are the known receptors for CCL28, which could promote tumor tolerance and angiogenesis." (PMID 27086913, 2016). "CCR3 was also expressed in the tumor, but we did not detect expression of its ligand." (PMID 25123545, 2014). "Blocking of chemokine receptor CCR2 but not CCR1, CCR3, CCR5, CCR7 or CXCR3 on CTL007 with Abs significantly inhibited tumor cell apoptosis." (PMID 21450101, 2011). "The high expression of CCR3 and LDHA in tumor tissue is not prominent." (PMID 38511143, 2024). "Although multiple studies across different neoplasms have shown elevated levels of eotaxins correlate with TATE, unlike homeostatic or allergic conditions, eosinophils can migrate to tumor sites without requiring CCR3." (PMID 37587450, 2023).
infection (50 papers, 2005 to 2025). The state of being infected such as from the introduction of a foreign agent such as serum, vaccine, antigenic substance or organism. "The gene for the neutrophil-recruiting chemokine CXCL3 was also increased with infection, whereas CCR3, associated with monocyte recruitment, was decreased." (PMID 40682363, 2025). "Microglia are susceptible to infection as they have both co-receptors (CCR3 and CCR5) on their surfaces, with CCR5 more strongly associated with virus entry and subsequent development of dementia." (PMID 31614895, 2019). "CCR3 deficiency rendered mice susceptible to the development of chronic B. malayi adult infections, including permissiveness to fecund infections able to complete the filarial parasite life cycle +84dpi." (PMID 29547639, 2018). "Interestingly, a high frequency of CCR3 usage during primary infection has been detected by direct cloning and expression of viral sequences, while in vitro culture apparently selects against CCR3 usage leading to the expansion of variants with exclusive CCR5 usage." (PMID 21284904, 2011). "Our data indicate that CCR3 is the primary CCL28 receptor expressed in neutrophils during STm infection." (PMID 39193987, 2024). "We conclude that CCR3 is stored intracellularly in neutrophils and rapidly mobilized to the cell surface upon infection, phagocytosis, and/or cytokine stimulation." (PMID 39193987, 2024). "Our results indicate that CCL28 contributes to neutrophil accumulation and activation, with its receptors CCR3 and CCR10 upregulated in the mucosa during infection, where up to ~50% of neutrophils express surface CCR3." (PMID 39193987, 2024). "The rapid surface expression of CCR3 on neutrophils upon infection suggests that the receptor is stored intracellularly, similar to eosinophils." (PMID 39193987, 2024). "Th2 cells express CCR3, which acts to bind chemokines and direct their migration towards the site of injury or infection." (PMID 38332938, 2024). "Upon STm infection in vitro, bone marrow neutrophils increased CCR3 surface expression as quickly as 5 min post-infection, reaching a maximum of ~30% CCR3+ neutrophils at 2 hpi." (PMID 39193987, 2024). "Neutrophil CCR3 is stored in intracellular compartments and rapidly mobilizes to the cell surface during infection." (PMID 39193987, 2024). "The number of repressed CCR3+Siglec‐F+ eosinophils and eosinophil marker genes in the mS6KO mice were indeed restored by Ad‐Sirt6 infection." (PMID 34125994, 2021). "Not only is the presence of CD4 required for HIV-1 to enter a CNS cell, but the CXCR4 or CC-chemokine receptor 5 (CCR5) co-receptors and CC-chemokine receptor 3 (CCR3) receptors are also required to produce effective infection." (PMID 34440127, 2021). "We utilized a CCR3 neutralising antibody to temporarily deplete CCR3+ cells in WT mice prior to infection." (PMID 29547639, 2018). "Infection of CCR3-/- mice also induced a high-level induction of RELMα expression in expanded peritoneal Mφ." (PMID 29547639, 2018). "We therefore tested the ability of SIVsmm envelopes to mediate infection through human CCR2b, CCR3, CCR8, GPR1, GPR15 (BOB), CXCR6 and CXCR4." (PMID 20865163, 2010). "In SARS-CoV infected CB DCs, a strong and significant upregulation was observed for CCR-3 at both 3 h and 9 h post infection." (PMID 19505311, 2009). "Furthermore, several studies have shown that exposure to LPS or influenza A induces CCR3 acquisition in infiltrated neutrophils in the lungs during inflammation or infection." (PMID 40650924, 2025). "MSCs typically do not express CCR3, but following infection with Kaposi’s sarcoma-associated herpesvirus (KSHV), they exhibit increased CCR3 expression and enhanced migration ability in vitro." (PMID 39271680, 2024).